CXCR4 (C-X-C motif chemokine receptor 4)
Diseases named in the same sentence as CXCR4 in open-access papers (continued):
Sharing a sentence is not in itself a finding about the gene and the disease.
cancer (continued). "With the increasein importance of CXCR4 as a therapeutic target for cancer, as wellas its relevance in HIV-1 entry and several autoimmune diseases, comesa need for chemical tools to study this receptor." (PMID 36944083, 2023). "In cancer, the CXCR4 pathway, induced by the binding of its ligand CXCL12, was identified to promote metastasis and angiogenesis, and to regulate immune dysfunction." (PMID 37513979, 2023). "As the CXCL12/CXCR4 axis mediates the interaction between stromal cells and cancer cells in TME, our study aimed to identify the therapeutic potential of curcumin by focusing on its inhibitory effect on breast TME." (PMID 38004606, 2023). "CXCR4 is a cell-surface receptor that has been described as being overexpressed in more than 20 cancer types, including hematologic and solid neoplasias, and is the chemokine receptor most commonly expressed by cancer cells." (PMID 36986589, 2023). "NF-κB has been suggested as a transcription factor regulating CXCR4 expression and it was shown that CXCR4 expression is dependent on the activation of the NF-κB pathway in several cancer types." (PMID 37853467, 2023). "This technique was deployed in order to show the extravasation of CXCR4-expressing MDA-MB-231 cancer cells over a confluent HUVEC monolayer in the presence of a CXCL12 chemokine gradient." (PMID 37386445, 2023). "Elevated SDF-1 levels have rapidly recruited bone marrow-derived progenitors and CXCR4-expressing cancer cells to the pre-metastatic niche." (PMID 38067195, 2023). "On the contrary, the increased expression of CXCL12, a ligand for CXCR4, facilitates the escape of cancer cells from dormancy." (PMID 37173977, 2023). "Their findings also showed that A2A receptor stimulation inhibited CXCR4 expression and that A2A receptor agonists and CXCR4 antagonists protected nude mice from the metastasis of malignant tumor cells in vivo and prolonged their survival time." (PMID 36825149, 2023). "The binding of CXCL12 to CXCR4 on cancer cells promotes their growth, survival, and migration, which contributes to cancer progression and metastasis." (PMID 37538932, 2023). "CXCR4 plays a crucial role in tumor development, proliferation, and metastasis mainly by contributing to the establishment of cancer stem-like cell supporting niches and the chemotactic directing of cancer cells to those microenvironments." (PMID 37853467, 2023). "It was reported that high CXCR4 expression corresponds to bad prognosis for breast, lung and colorectal cancers contradicting TCGA-based findings." (PMID 37006265, 2023). "CXCL12 is a chemokine released by cancer-associated fibroblasts, tumors, and normal cells that promotes the motility and migration of cancer cells expressing its membrane receptor CXCR4." (PMID 37227446, 2023). "The chemokine and receptor are expressed almost ubiquitously in human tissues and cells throughout life, and abnormal expression of CXCL12 and CXCR4 is observed in pathological conditions, such as inflammation and cancer." (PMID 37141381, 2023). "Some drugs that target CXCR4 have been developed for cancer treatment, such as plerixafor (AMD3100), which prevents the binding of CXCL12 to CXCR4 and thus inhibits the growth and spread of cancer cells." (PMID 37538932, 2023). "Some of these molecules are targeted by the approved or experimental anti-cancer drugs (such as plerixafor for CXCR4 or tocilizumab for IL6R)." (PMID 37006265, 2023). "When CXCR4 expression was evaluated using the the Cancer Gene-Expression Miner -bc-GenExMiner v.4.8 tool, we observed that its expression was significantly higher in ERα-positive/PR-negative tumors when compared to ERα-positive/PR-positive tumors (P < 0.0001)." (PMID 37550554, 2023). "Our study showed that curcumin is a potent anti-cancer agent that can remodel the breast TME, thereby restricting the ADMSC-cancer positive feedback loop associated with the CXCL12/CXCR4 axis." (PMID 38004606, 2023).
cancer (continued). "CXCR4 was discovered to be overexpressed in a variety of cancer cells in response to hypoxia, hence contributing to cancer metastases." (PMID 37460927, 2023). "These cancer cells express C-X-C chemokine receptor type 4 (CXCR4), IGF1R, and have high Src activity, making them more likely to metastasize to bone." (PMID 38041134, 2023). "EMU-116 is an orally bioavailable small-molecule CXCR4 antagonist under development for the treatment of cancer." (PMID 37475868, 2023). "CXCR4 is highly expressed in many types of cancer cells, and elevated CXCR4 levels correlate with distant metastases, poor prognosis, and unfavorable outcomes in most solid tumors." (PMID 37490147, 2023). "It has been proven that the transfer of CXCR4 by PMPs enhances the proliferation and migration of recipient cancer cells." (PMID 36882818, 2023). "Cpd3 alone significantly reduced the CSC content defined as CD133+CD44+ or CD133+CXCR4+ cancer cells, whereas gemcitabine treatment increased the CSC content." (PMID 38012687, 2023). "Increased levels of both CXCL12 and CXCR4 in cancer cells and the related microenvironment are frequently observed and are responsible for cell proliferation and metastasis, indicating their utility as cancer biomarkers." (PMID 37141381, 2023). "After docetaxel and androgen deprivation treatment, prostate cancer cells secreted more CXCL12 via TAMs,386 which helped cancer cells survive and reduced their sensitivity to chemotherapy by activating CXCR4." (PMID 37211559, 2023). "CXCR4 (C-X-C chemokine receptor type 4) is the most commonly expressed of all chemokine receptors in malignant tumors." (PMID 36308553, 2023). "In summary, our pan-cancer approach showed a prominent role for CXCR4 as immune marker in solid tumors." (PMID 36672341, 2023). "Mesothelin (MSLN) and C-XC chemokine receptor 4 (CXCR4) are membrane-bound proteins, expressed in certain cancers, and thus are promising targets for endo-radiotherapy." (PMID 37047331, 2023). "CXCR4 is a well-characterized chemokine receptor that regulates cancer metastasis, including SCLC metastasis." (PMID 36597126, 2023). "CXCR4 expression was correlated with validated pathologic prognosticators, clinical data, and overall and cancer-specific survival." (PMID 36982302, 2023). "The current study provides novel knowledge that revealed the γ-mangostin effect on suppressing CXCR4 transcription, thereby inhibiting cancer cell migration and cell proliferation." (PMID 38655233, 2023). "In adult human testes, CXCL12 is predominantly expressed by Sertoli cells, while CXCR4 is expressed by normal spermatogonial and meiotic germ cells, as well as most cancer cells." (PMID 36614308, 2023). "At the same time, CXCR4 expression was largely restricted to cancer cells in these lesions and appeared unchanged after irradiation." (PMID 36831366, 2023). "Taken together, these results suggest that the LPA1 activation inhibits CXCL12-induced migration in cancer cells that endogenously express both CXCR4 and LPA1." (PMID 37749552, 2023). "Our findings suggest that curcumin has great value as an anticancer agent that can remodel breast TME by limiting ADMSC-cancer interaction through regulation of the CXCL12/CXCR4 axis." (PMID 38004606, 2023). "By adding an anti-PD-L1 agent to the CXCR4 blockade, a significant decrease in cancer cells was observed, suggesting a synergistic effect when combining ICIs with CXCR4 or CXCL12 antibodies." (PMID 37895882, 2023). "ICAM1+ neutrophils are generally considered to have anti-cancer effects while CXCR4+ neutrophils exert the opposite effect." (PMID 37644468, 2023). "Some previous studies have reported that mast cells express different chemokine receptors, such as CCR2, CCR5, CXCR1, or CXCR4, in different cancers (19-, 21)." (PMID 37042867, 2023).
cancer (continued). "This differentiation occurred through cancer cell induced TGFβ-dependent upregulation of CXCR4 in monocytes while CXCL12 expressed by perivascular fibroblasts attracted these motile TAMs toward the blood vessels, bringing motile cancer cells with them." (PMID 37261345, 2023). "Compared to monolayer cultures, NB spheroids were characterized not only by significantly higher expression of a subgroup of CSC markers, including CXCR4, NANOG and BMI1, but also increased T389 phosphorylation of cancer-associated RNA-binding protein La." (PMID 36980635, 2023). "Accordingly, a comprehensive understanding and targeting of CXCL12/CXCR4/NF-κB/SHH signaling holds great importance in treating cancer." (PMID 38004606, 2023). "Another study has explored the translocation domain of diphtheria toxin (TD: blocks CXCR4 downstream signaling pathways), as a functional domain in CXCR4-targeted oligomeric nanoparticles designed for cancer treatment." (PMID 38004925, 2023). "For example, decreased expression of CXCL12 was associated with unfavorable overall survival (OS) and disease-free survival (DFS) in all types of cancer, whereas CXCR4 was highly expressed in several cancer types." (PMID 37198402, 2023). "CXCR4 has been a promising cancer target for years and it is an especially interesting anti-metastatic target as it is one of the factors involved in bone-homing of cancer cells." (PMID 37475868, 2023). "In this study, we demonstrated that LPA1 unidirectionally inhibits CXCR4 not only in the heterologous expression system but also in various cancer cells endogenously expressing both receptors." (PMID 37749552, 2023). "The role of CSCs in PDAC metastasis was also studied, identifying chemokine (C-X-C motif) receptor 4 (CXCR4) co-expression as a driving factor of cancer cell migration and metastasis." (PMID 37108193, 2023). "Either siRNA silencing or CRISPR-Cas9-based knockout of AHR prevented expression of CYP1A1, but amplified the expression of MMP9, CXCL12 and CXCR4 that contribute to the tumorigenesis and metastasis of the cancer cells." (PMID 37151890, 2023). "Owing to its role in cancer metastasis and progression, the CXCL12/CXCR4 axis is an important target for cancer therapy." (PMID 38004606, 2023). "We further examined expression levels of CXCR4 and immune-related bona fide gene candidates within the pan-cancer cohort." (PMID 36672341, 2023). "We also provide evidence for the first time that in cancer cells endogenously expressing CXCR4 and β2AR, the two receptors co-localize and exhibit functional synergy." (PMID 37878624, 2023). "In this review, we would like to summarize the implementation of CXCR4-targeted radiopharmaceuticals in the field of various kinds of carcinomas." (PMID 37375261, 2023). "Similar to other types of cancer, in EwS, CXCL12 was found to be essential for neovascularization and increased expression of CXCR4 was found to be associated with metastasis phenotype." (PMID 36230825, 2022). "Among these, there is growing interest in the role of CXCL12, CXCR4, and FAPα expression in cancer because of their immunosuppressive and procancer properties 50-52." (PMID 34976180, 2022). "In this study, we report our development of a protein MRI contrast agent (ProCA32.CXCR4) which can bind to CXCR4 expressed in cancer cells and liver metastases." (PMID 35145271, 2022). "Earlier studies have reported that FK866 is a NAMPT inhibitor and controls cancer progression by a downregulation of TNFα, IL-6 expressions, CXCR4." (PMID 36497496, 2022). "Scavenging of CXCL12 by ACKR3 has also been shown to promote growth and metastasis of CXCR4+ breast cancer cells and is thought to contribute to the progression of other cancers." (PMID 35857509, 2022).
cancer (continued). "CXCR4 cyclotide antagonists can also be used as bioimaging agents for visualizing cancer tumors expressing high levels of CXCR4 protein." (PMID 36234971, 2022). "The mechanism of CXCR4 overexpression induced cell metastasis has been studied in several types of cancer." (PMID 36103228, 2022). "CXCR4 has been shown to play a crucial role in the dissemination and extraversion of various types of cancer cells and the formation of liver metastases." (PMID 35145271, 2022). "Several genes associated with cancer cell motility, including SEMA5A, PDGFRB, TGFB2, CXCR4, SNAI1, ICAM1, and NEDD9, were decreased in shGPR81 cells." (PMID 35428832, 2022). "The chemokine receptor CXCR4 in adipose tissue is expressed on adipocytes and is highly expressed in various types of cancers by inducing chemotactic and invasive responses and mediating actin polymerization and pseudopodia formation." (PMID 35481418, 2022). "An increase in mRNA expression of CXCL12, CXCR4, and FAPα was observed in residual cancer tissues after nCRT treatment." (PMID 34976180, 2022). "CXCR4 overexpression was found to be a marker for bone metastases in many cancer cells, including breast and prostate cancer, where it facilitates metastatic colonization and survival in the bone microenvironment." (PMID 36497192, 2022). "Other chemokines and receptors, such as CCL2, CCR5, and CXCR4, have also been used in combination with other drugs in a variety of cancers." (PMID 35770088, 2022). "Here, we designed a nanobody molecule with bi-targeting on PD-L1 and CXCR4, as both targets are overexpressed in many cancer cells and play important roles in tumorigenesis." (PMID 36284271, 2022). "Studies have reported that CXCR4 and integrin αvβ3 are synergistically involved in cancer metastasis." (PMID 36145541, 2022). "Previous studies have shown that intracellular delivery of siRNA to knockdown CXCR4 expression in cancer cells is an effective therapeutic strategy." (PMID 35630915, 2022). "In agreement with the demonstrated role of hypoxia in inducing CXCR4 expression in cancer, we found CXCR4 the most significantly upregulated gene by hypoxic conditions, independently of inflammatory stimuli." (PMID 35216235, 2022). "Targeting CXCR4 with radiopharmaceuticals has emerged as a viable method of identifying and potentially treating patients with CXCR4-expressing cancers, with [68Ga]Ga-Pentixafor and [177Lu]Lu-/[90Y]Y-Pentixather leading the way in clinical studies." (PMID 35890397, 2022). "ProCA32.CXCR4 has been shown to bind to overexpressed CXCR4 on cancer cell lines such as M20-09-196 and Mel290, using immunofluorescence staining." (PMID 35145271, 2022). "Taken together, these results suggest that the insulin-activated CXCL12/CXCR4 axis sustains a paracrine feedforward loop coupling cancer and stromal cells, thus fostering a motile phenotype in BCAHC-1 cells." (PMID 35672854, 2022). "The expression of chemokine receptors varies among cancer cells of different origins, but CXCR4 is widely expressed in human cancers." (PMID 35630915, 2022). "CAFs also secrete CXCL12 (also known as stromal cell-derived factor 1, SDF1), which is a canonical ligand for the chemokine receptor CXCR4, to promote the growth and angiogenesis of CXCR4-expressing cancer cells." (PMID 35884382, 2022). "Cancer-activated fibroblasts (CAFs)-released CXCL12 chemokine activates CXCR4 and/or CXCR7 receptors and regulates PDAC cell proliferation, migration, and invasion." (PMID 36359736, 2022). "Together with its ligand CXCL12, CXCR4 plays critical role in cancer progression especially metastasis." (PMID 36230825, 2022). "Among them, chemokine (C-X-C motif) receptor 4 (CXCR4) and integrin αvβ3 are involved in several key biological processes of cancer and have been extensively investigated as molecular imaging targets." (PMID 36145541, 2022). "The C-X-C chemokine receptor 4 (CXCR4) is a chemokine receptor that is highly expressed in over 20 subtypes of cancers." (PMID 35890397, 2022).
cancer (continued). "A new therapeutic approach of targeted therapy can attack cancer cells through the SDF-1/CXCR4 axis, which is a fundamental driving force for tumor cell growth and survival." (PMID 35056696, 2022). "Since stromal-vascular BM niches secrete abundant CXCL12, whereas CXCR4 is primarily expressed on HSCs and malignant cells, the CXCL12/CXCR4 axis becomes a key pathway for both normal hematopoiesis and cancer cell homing to the BM." (PMID 36428753, 2022). "C-X-C motif chemokine receptor 4 (CXCR4) belonged to the C-X-C chemokine receptor family is related to various cancers." (PMID 35388021, 2022). "CXCR4 expression/overexpression has been detected in various cancer histotypes, including lung, pancreatic, colon, breast, renal and prostate histotypes, which are derived from CSCs." (PMID 35681259, 2022). "Tumors also showed high Ki67 expression that indicated high proliferative activity and also a high membrane CXCR4 levels in cancer epithelial cells as we had already observed in vitro." (PMID 35884987, 2022). "The CXCL12/CXCR4 axis has been identified as a target for drug development in oncology due to its critical role in promoting and maintaining cancer stem cells." (PMID 36140541, 2022). "There was a significant correlation of the CXCL12 levels in plasma membrane expression and CXCR4 and FAPα levels in the cancer cells of LARC after nCRT group (Spearman's Rho: p = 0.001 and p = 0.003)." (PMID 34976180, 2022). "A CXCR4 antagonist is another way to target the SDF-1/CXCR4 axis for cancer treatments with an overexpression of the SDF-1/CXCR4 axis such as in MM." (PMID 35056696, 2022). "There are many other small molecule CXCR4 inhibitors for cancers in development, namely small peptide molecule and small nonpeptide molecule inhibitors." (PMID 36254250, 2022). "Experiments confirmed that CXCR4 was related to the pathogenesis or prognosis of GC and other malignant tumors 14,26,27." (PMID 35388021, 2022). "CXCR4 is an important chemokine that is overexpressed in cancer cells and is involved in the proliferation of cancer cells." (PMID 36551144, 2022). "SDF-1/CXCL12 is the primary secretome of CAFs, which promotes cancer growth by interacting with CXCR4 in cancer cells." (PMID 36042526, 2022). "It is well-established that CXCR4 is overexpressed in over 23 different cancer types, and that PD-1 is expressed not only on immune cells but also in several different cancer cells." (PMID 35797269, 2022). "Consistently, we observed a highly evident GSDMD translocation to the membrane of CXCR4+ SW1417 cells with very high intensity in 10–20% of exposed cancer cells, mainly after 48 hours of exposure to T22-PE24-H6." (PMID 35532120, 2022). "For example, in humans, CXCR4 mRNA levels in blood sEVs, secreted from cancer cells, are increased in patients with breast cancer." (PMID 35632763, 2022). "Yet, given the findings that CXCR4 expression often correlates with malignancy grade, plerixafor-responsive cancer patients presumably would have had otherwise unfavorable prognoses." (PMID 36568151, 2022). "In a PDAC mouse model, administration of a CXCR4 inhibitor AMD3100 (plerixafor) led to T cell accumulation among cancer cells with a synergistic tumoricidal effect when combined with a PD-L1 antagonist." (PMID 36077755, 2022). "In this framework, the T22-DITOX-H6 nanotoxin represents a promising approach for HNSCC treatment, as it aims to deliver cytotoxic compounds exclusively to CXCR4+ cancer cells." (PMID 35456719, 2022). "Significantly, the CXCL12/CXCR4/CXCR7 axis functionally contributes to cancer cell motility, invasiveness, and metastasis." (PMID 36568151, 2022). "As a result, CXCL12/CXCR4 antagonists have currently been developed to impair pathological procedures and also disrupt cancer cell adhesion to the stromal cells." (PMID 34980128, 2022). "In this framework, repeated T22-DITOX-H6 administration effectively eliminated the CXCR4+ HNCSS cancer cells in the invasive front of the primary tumors." (PMID 35456719, 2022).